GZMB (granzyme B)
Diseases named in the same sentence as GZMB in open-access papers (continued):
Sharing a sentence is not in itself a finding about the gene and the disease.
COVID-19 (continued). "The differential expression analysis identified six differentially expressed genes (DEGs) shared by myasthenia gravis (MG) and COVID-19, namely SAMD9, PLEK, GZMB, JUNB, NR4A1, and NR1D1." (PMID 38384322, 2023). "In the peripheral blood mononuclear cells of patients with severe COVID-19, in addition to CD8+ lymphocyte dysfunction, significantly higher granzyme B and perforin expression was observed in CD8+ lymphocytes compared with mild disease." (PMID 37376562, 2023). "Along with the depletion and hyperactivation of T cells, an elevated granzyme B level and a tendency to an increased TCR-independent functional activity were observed in CD56+ cells of patients with COVID-19." (PMID 37240393, 2023). "In the present study, we identified six shared genes (SAMD9, PLEK, GZMB, JUNB, NR4A1, and NR1D1) of MG and COVID-19 patients through bioinformatic analysis." (PMID 38384322, 2023). "PD-L1 was higher in severe COVID-19 patients, whereas the levels of CD40 ligand and granzyme B showed a significant increase in mild-moderate COVID-19 patients, but reduced in severe patients." (PMID 35529862, 2022). "Nevertheless, increased expression of NKG2A led to the reduced levels of CD107a (degranulation marker), IFN-γ, IL-2, granzyme B, and TNF-α in NK cells from COVID-19 patients." (PMID 36505489, 2022). "A controversial role is played in COVID-19 by CD8+ T cells with reduced levels of CD107a, IFN-γ, IL-2, and granzyme B compared to healthy cells, or by CD8+ T cells with increased production of granzyme A and B and perforin during COVID-19." (PMID 36359755, 2022). "Whereas NK cells from COVID-19 WARD patients show an increase in PRF, GZMA, and GZMB, levels were decreased in ICU patients." (PMID 36275702, 2022). "CD4 T-cells with cytotoxic activity (CD4 CTLs) and NK-cells displayed enhanced interferon signaling and effector activation markers (GZMB, GZMH, CCL4, XCL2) in patients who succumbed to COVID-19." (PMID 35169146, 2022). "In the acute phase of COVID-19, SARS-CoV-2-specific CD8+ T cells expressed activation markers (CD38 and HLA-DR) and secreted cytotoxic molecules (perforins and granzyme B), indicating these cells were activated with cytotoxic functions." (PMID 36505489, 2022). "Recent study reported mucosal-associated invariant T (MAIT) cells in particularly are highly activated in COVID-19 patients, and corelated with cytotoxicity by producing IFN-γ, Granzyme B, TNF-α cytokines, and with the severity and mortality of SARS-CoV-2." (PMID 36825215, 2022). "In contrast, CD4 CTL T-cells and NK-cell subsets displayed increased expression of effector activation markers (GZMB, GZMH, CCL4, XCL2) and ISGs in patients who succumbed to COVID-19." (PMID 35169146, 2022). "NKG2A expression is upregulated on NK cells and CTLs in COVID-19 patients, with a decreased capacity to produce CD107a, IFN-γ, IL-2, granzyme B and TNF-α., which suggests functional exhaustion of cytotoxic lymphocytes in COVID-19 patients." (PMID 35833134, 2022). "Pulmonary infiltrating CD4 T cells with cytotoxic capacity, as measured by Granzyme B, identified in our PTM and recently in humans with severe COVID-19, are a unique and possibly understudied aspect of the disease." (PMID 34929014, 2021). "Upon stimulation with IL-12/IL-18, the percentage of Granzyme B (p = 0.007), IFN-γ (p = 0.008), TNF-α (p < 0.001) and Perforin (p = 0.03) expressing MAIT cells was significantly lower in COVID-19 patients compared to control uninfected individuals." (PMID 34238985, 2021). "In this study, we analyzed the gene expression pattern of cytotoxic proteins (PRF1, GZMB, GNLY, GZMA, GZMK), cytokine (IFN-γ), and apoptotic protein (FASL) in CD8+ T cells from the peripheral blood of COVID-19 patients." (PMID 34945761, 2021). "Analyses of growth factors showed significantly higher levels of VEGF, Granzyme B and PDL1 in PIMS-TS children compared to COVID-19, seropositive and control children." (PMID 33813138, 2021).
COVID-19 (continued). "MAIT cells of COVID-19 patients also had lower expression levels of TNF-alpha, perforin and granzyme B upon stimulation with IL-12 + IL-18." (PMID 34238985, 2021). "We show that plasma CXCL2, CXCL10, CCL5, CD40 ligand, IL-10, and GM-CSF concentrations and ELF CXCL1, CXCL10, granzyme B, TRAIL, and EGF concentrations were found in greater concentrations in COVID-19 than in non-COVID-19 ARDS patients." (PMID 33138839, 2020). "The percentages of granzyme B+ and IFN-γ+ cells among CD8+ T cells were significantly higher in the influenza group than in the COVID-19 group." (PMID 32651212, 2020). "In COVID-19 patients, the majority of the CD73-CD8+ T cells were capable of secreting granzyme B, perforin, tumor necrosis factor (TNF-α) or interferon-gamma (IFN-γ)." (PMID 32707842, 2020). "S2, C and D) were also identified as DEGs in BAL NK cells of COVID-19 patients as compared with controls, including GZMB (granzyme B), PRF1 (perforin), HAVCR2 (Tim-3), and CCL4 (MIP-1β)." (PMID 32826343, 2020). "A trend toward higher ELF concentrations of CXCL1 (p = 0.287), CXCL10 (p = 0.287), granzyme B (p = 0.110), TRAIL (p = 0.094), and EGF (p = 0.094) is observed in COVID-19 patients." (PMID 33138839, 2020). "We further quantified the proportion of cytotoxic CD8+ T cells (defined as perforin+ granzyme B+ memory CD8+ T cells) in a subset of HD and severe COVID-19+ individuals." (PMID 32669287, 2020). "COVID-19 patients had higher frequencies of CD8+ T cells producing the cytotoxic molecules GzmA and GzmB as well as perforin than healthy controls." (PMID 32948688, 2020). "Together with decreased levels of TNF-α, granzyme B, and IFN-γ, cell markers such as NKG2A in NK cells may indicate a mechanism that both exhausts NK cells in COVID-19 patients and prevents their production." (PMID 40497938, 2025). "However, the frequency of T CD8+ cells double-positive for Granzyme B and Perforin increased in both COVID-19 and LTBI/COVID-19 compared to HD upon spike stimulation (p<0.05), and COVID-19 maintained this high frequency with BCG/spike stimulation (p<0.05)." (PMID 40458413, 2025). "Patients with mild COVID-19 exhibited expanded subsets of unconventional CD56dimCD16- NK cells with elevated NKG2D expression and lower levels of cytotoxic mediators (granzyme A, granzyme B, and granulysin)." (PMID 40421029, 2025). "Serum Granzyme B production has been found to be enhanced in MIS-C patients compared to uncomplicated COVID-19 and in MIS-C patients without myocarditis compared to MIS-C with myocardiac involvement." (PMID 39594853, 2024). "MAIT cell PD-1 expression at 4 mo after resolution of acute COVID-19 correlated negatively with GzmB expression following IL-12+IL-18 stimulation, a pattern not replicated in the HD group." (PMID 38117799, 2024). "The study of the frequency of GZMB, CD107a, CD39, PD-1 and TIGIT-expressing Treg cells did not reveal any distinctive pattern in COVID-19 patients associated either with infection or with disease severity." (PMID 37809093, 2023). "In our study, no significant changes in the intracellular granzyme B level were observed in the total T cell population during the progression of COVID-19." (PMID 37240393, 2023). "Elevated granzyme B expression was observed in Tregs in samples stimulated with Pool Spike CoV-2 in Mild Recovered volunteers who did not have arthralgia during acute COVID-19 than in those who did." (PMID 36969257, 2023). "Regardless of myopericarditis development, the COVID-19 mRNA vaccine caused an increase of NK cell number and gene expression associated with effector function such as IFN-γ (IFNG), granzyme A (GZMA), and granzyme B (GZMB) compared with healthy controls." (PMID 35251049, 2022).
COVID-19 (continued). "We then investigated CD4+, Treg and CD8+ T cells polyfunctionality by analyzing simultaneous production of TNF-α, CD107a, IFN-γ, IL-2, IL-17, granzyme-B and TGF-β by mild, moderate and severe COVID-19 convalescent patients at recovery time-point I and time-point II, as well as by healthy donors." (PMID 35757700, 2022). "In acute COVID-19, SARS-CoV-2-specific CD8+ T cells exhibit high levels of IFN-γ, granzyme B, perforin, and CD107a molecules, some of which are present in the cytotoxic granules and are associated with potent cytotoxic effector functions, developing fast CD8+ T cell responses." (PMID 35833134, 2022). "Indeed, NK cells and CD8+ T cells in BAL fluid from COVID-19 patients displayed increased transcript expression levels of GZMA, GZMB, and PRF1 even in patients with moderate disease." (PMID 35371005, 2022). "Furthermore, there was a trend toward higher mRNA expression of other cytotoxic proteins, GNLY and GZMB, in CD8+ T cells in mild COVID-19 patients with stable clinical appearance." (PMID 34945761, 2021). "Furthermore, the expression of CD94/NK group 2 member A (NKG2A) was increased on cytotoxic T lymphocytes (CTLs) and NK cells in COVID-19 patients, accompanied by low levels of CD107a, IFN-γ, IL-2, TNF-α, and granzyme B." (PMID 33987176, 2021). "Higher levels of APRIL and BAFF, fundamental survival factors for different B-cell types, were found in pregnant COVID-19 women compared with those without infection, as well as granzyme B (GRZB), a serine protease released by NK and cytotoxic T cells." (PMID 34326336, 2021). "GZMB was highly expressed in CD8 + T-cells and NK T-cells of the severe COVID-19 group." (PMID 34239034, 2021). "PIMS-TS children had significantly elevated levels of cytokines, IFNγ, IL-2, TNFα, IL-1α, IFNα, IFNβ, IL-6, IL-15, IL-17A, GM-CSF, IL-10, IL-33 and IL-Ra; elevated chemokines, CCL2, CCL19, CCL20 and CXCL10 and elevated VEGF, Granzyme B and PDL-1 in comparison to COVID-19, seropositive and controls." (PMID 33813138, 2021). "To characterize their cytotoxic profile, we stained the total CD4+ T cells directly ex vivo without restimulation for the cytotoxic molecules GzmA, GzmB, and perforin and compared the two age groups between COVID-19 patients and age-matched healthy controls." (PMID 32948688, 2020). "However, for GzmB and perforin, we found a higher frequency of positive cells among PD-1+ CD8+ T cells in the group of younger COVID-19 patients than in healthy controls." (PMID 32948688, 2020). "In a study using HLA-A02 tetramer, antigen-specific CD8+ T cells (obtained from COVID-19 acute-phase patients) responding to the S269–277 epitope of the spike protein predominantly belonged to the subpopulation simultaneously expressing GZMA, GZMB, GZMK, and perforin." (PMID 36685601, 2022). "Based on the granzyme ratio between granzyme A and granzyme B, we have observed that COVID-19 patients with non-severe forms of the disease presented a higher capacity for granzyme A secretion and a lower capacity for granzyme B secretion, contrary to their severe counterparts." (PMID 35743021, 2022). "The CXCL9–CXCR3 axis, which was upregulated in COVID-19, is thought to be involved in the recruitment of Th1 and CD8+ lymphocytes to sites of inflammation in COPD, with the subsequent immune-mediated lung damage occurring through the production of perforins and granzyme B." (PMID 35743918, 2022). "On the other hand, it was evidenced that the quantity of lung parenchymal CD8+ T cells was not prominently increased during severe COVID-19 compared to the control group, albeit the majority of such cells expressed the PD-1 molecule, but they virtually lacked intracellular granzyme B expression." (PMID 36146713, 2022).
COVID-19 (continued). "The interrelationship of immune cells in COVID-19 was intrinsically identified, whereby T cells secreting IL-2, IL-4, and IL-17A were enriched among CD28+ and CD57− cells and cells secreting perforin/granzyme B/IFN-γ/tumor necrosis factor alpha (TNF-α)-expressed markers of terminal differentiation." (PMID 34488453, 2021). "Additionally, we provide a number of early prognostic markers for the onset of severe COVID-19, such as CD14+/CD16+ monocytes ratio, CD4+/CD8+T cell ratio, GZMK+/GZMB+ T cell ratio, etc., although these parameters require further validation in the larger cohorts." (PMID 35095917, 2021). "However, a trend of higher mRNA expression of cytotoxic protein PRF1 and GZMB in COVID-19 patients at the fifth day of the disease was noticed." (PMID 34945761, 2021). "In a recent study we showed that COVID-19 patients generate a large number of polyfunctional antigen-specific T cells, expressing at least two of the pro-inflammatory Th1 cytokines TNF, IL-2, IFNγ or the cytotoxic granzyme B, after stimulation with M, N or S OPPs." (PMID 34228322, 2021). "Granzyme B, known for its role in inducing apoptosis in infected cells, helps control viral spread, while DPPIV, through its dual function in immune modulation and glucose metabolism, might have long-term implications for metabolic health in post-COVID-19 recovery​." (PMID 40557167, 2025). "Furthermore, recently it was discovered that natural killer (NK) cells and CD8+ T cells of patients with COVID-19 have a higher expression of the NK cell inhibitory receptor, NKG2A, which is characterized by lower intracellular amounts of CD107, IFN-γ, IL-2, TNF-α, and granzyme B." (PMID 36679947, 2023). "In contrast, in severe COVID-19, CD8+ T cells are not apparent, they show enhanced PD-1 expression, and there is no evident increase in the amount of Granzyme B+ CD8+ T cells in the lung parenchyma." (PMID 36679947, 2023). "Expression of granzyme B and perforin was highest in lung-homing receptor-negative CD8+ T cells in healthy controls as well as in COVID-19 and influenza patients." (PMID 35371005, 2022). "A recent report demonstrated the secretion of Granzyme B by CD4+ and CD8+ T cells isolated from COVID-19 patients although without the co-expression of CD107 and TNFα, suggesting an exhaustion state of these cytotoxic cells." (PMID 34436366, 2021).
breast cancer (110 papers, 2003 to 2025). A primary or metastatic malignant neoplasm involving the breast. "Intriguingly, the TIME of Ing4-deleted mouse mammary tumors consisted of increased tumor-associated macrophages (TAMs) and decreased GzmB+CD4+ T cells." (PMID 38968186, 2024). "Breast cancers were found to decrease susceptibility to NK cell lysis by degradation of NK-derived granzyme B in autophagosomes under hypoxia." (PMID 39415291, 2024). "Of note, F-actin is able to rapidly and massively accumulate near the IS and thereby lead to the immune escape of breast cancer cells from NK-mediated cytotoxicity, which termed as actin response (AR), causing the decreased intracellular level of Granzyme B." (PMID 39741300, 2024). "Supportive of the functional contribution of the TIME in ING4-deficient tumor progression, low GZMB gene expression together with low ING4 expression was significantly associated with poor patient survival outcomes in the basal subtype of breast cancer." (PMID 38968186, 2024). "Specifically, ERα+ tumor cells from liver and breast cancer were treated with E2, which subsequently caused an upregulation of Granzyme B proteinase inhibitor-9 (PI9)." (PMID 32133288, 2020). "Next, focusing on data from the entire cohort of patients with breast cancer, we found that high coexpression of IL-31Ra, IL-4, IL-2, and Granzyme B was associated with increased survival, with results almost reaching statistical significance (p=0.056)." (PMID 32843492, 2020). "Low expression of the Granzyme B gene (GZMB) in combination with ING4-deficiencies was significantly associated with poor patient survival in the basal subtype of breast cancer, supportive of the clinical significance of granzyme-B-positive immune cell depletion in ING4-deficient tumors." (PMID 38968186, 2024). "A similar elevation in GZMB levels was demonstrated in a breast cancer transplant model in Il1b-deficient mice, where a combination of anti–IL-1β synergized with anti–PD-1 antibodies to restore the function of anergized antitumor T cells and resulted in complete inhibition of tumor growth." (PMID 37733448, 2023). "Trastuzumab treatment was associated significantly with an increase in tumor-associated NK cells and lymphocytes expressing granzyme B and TiA1, supporting a role for the immune response in the antibody mechanisms of action in patients with breast cancer receiving NAC." (PMID 34638242, 2021). "This improved environment promotes NK cell activation, leading to increased IFN-γ and GZMB production, ultimately augmenting tumor-specific immune responses against breast cancer cells." (PMID 40303301, 2025). "In solid tumors, such as lung and breast cancer, GZMB is extensively studied as a marker of anti-tumor immune activity." (PMID 41567188, 2025). "Tregs regulate NK cell activation in lymph nodes by blocking the release of GZMB and CD107a from NK cells, thereby promoting the lymphatic metastasis of breast cancer." (PMID 40303301, 2025).